BRAF (B-Raf proto-oncogene, serine/threonine kinase)
Diseases named in the same sentence as BRAF in open-access papers (continued):
Sharing a sentence is not in itself a finding about the gene and the disease.
tumor (continued). "In patients whose tumor harbors a BRAF mutation and who are not eligible for clinical trial participation, treatment with BRAF/MEK targeted therapy should be considered, and readers are referred elsewhere for guidance on administration of these agents." (PMID 29848375, 2018). "Therefore, it is plausible that factors associated with CRC risk and survival differ across tumor molecular subtypes defined by MSI and BRAF mutation status." (PMID 29409465, 2018). "The participation of BRAF in tumor progression was reported in many studies." (PMID 29455659, 2018). "We explored the BRAF and KRAS mutations (codon 12, 13, 59, and 61) in tumor tissues." (PMID 30509319, 2018). "Thus, the median CA 19-9 level was numerically high in patients with BRAF-mutant tumours and 50% of those with an isolated elevated CA 19-9 (low CEA) had BRAF-mutant tumours." (PMID 29872151, 2018). "All the tumor areas sampled were analyzed for KRAS, BRAF, PIK3CA, and NRAS mutations." (PMID 29774112, 2018). "Chemotherapy may be of benefit in heterogeneous tumours, where some cells are still sensitive to BRAF inhibition whilst the others acquired resistance." (PMID 29552321, 2018). "BRAF, a member of the RAF gene family, encodes a serine-threonine protein kinase that is a downstream effector of activated RAS, activating MEK (MAP2K) and leading to tumor initiation and progression via the activation of ERK (MAPK1)." (PMID 29690599, 2018). "Numerous experimental model systems have confirmed that RAS/BRAF abnormalities contributed to cell invasion and apoptosis suppression during metastatic cascade, which may bring about organ involvement and tumor progression." (PMID 29643917, 2018). "Similarly, treatment of FLT3L/poly I:C, which expands and induces the maturation and activation of CD103+ cDC1s at the tumor sites, has been shown to enhance anti-tumor responses and improve efficacy when combined with BRAF and PD-L1 blockade." (PMID 30619378, 2018). "In addition, we aimed to explore the prognostic value of RAS/BRAF gene status in CRC patients with primary tumor resected and with subsequent lines of chemotherapy." (PMID 29707525, 2018). "For instance, the potential neoantigen based on BRAF V600E mutation and HLA-A03:01 exists in 117 tumor samples, and corresponding neoantigens based on several mutations of KRAS and PIK3CA are also shared in more than 40 tumor samples." (PMID 30223042, 2018). "Early‐stage patients not qualifying for chemotherapy might be reconsidered for such treatment if their tumor has loss of CDX2 and mutated BRAF." (PMID 29900672, 2018). "Furthermore, the patient’s tumor harbored amplifications of BRAF, EGFR, MET, and CDK6, which provides a rationale for this tumor’s acquired resistance to the triple BRAF/MEK/CDK4&6 inhibitor treatment applied before sequencing." (PMID 30373609, 2018). "As for the mutational status of the KRAS, NRAS and BRAF genes, no discordance was observed between the primary tumours and the metastases." (PMID 30029640, 2018). "Briefly, BRAF may be involved in the development of tumor via other mechanisms, independent from the MMPs pathway." (PMID 30509240, 2018). "This is supported by the identification of BRAF mutations in a number of cases that failed to segregate, which likely represent Group 1 tumours when taken together with the observed enrichment of BRAF mutations within this group." (PMID 29058119, 2018). "However, infiltration of the tumor capsule was present in only 20% (4/20) of the BRAF-positive cases." (PMID 30200646, 2018).
tumor (continued). "We therefore tested whether a metformin/sitagliptin combination could also exert an effect in a murine tumor model with conditional melanocyte-specific expression of BRAF (V600E)." (PMID 29899823, 2018). "Due to the association of BRAF V600E mutation with AREG and EREG a Cox regression analysis using EREG and AREG levels as log-transformed continuous variables was performed and adjusted to age, gender and primary tumor location." (PMID 30467535, 2018). "Erastin is another anti-tumor agent that use VDAC as a docking site in mitochondria and induces oxidative, non-apoptotic death in human tumor cells with mutations in the oncogenes HRAS, KRAS, or BRAF." (PMID 29682501, 2018). "Overall, we found that the majority of the significant gene pair correlations were significant in only one of the groups, further indicating that the correlation strengths and overall transcriptional networks between TCGA BRAF V600E+ and BRAF− tumor samples are unique." (PMID 30042785, 2018). "The remaining five mutation positive Group 1 tumours lacking a BRAF mutation possessed an FGFR1, NF1, ARID1B, HIST1H3B, and ATM mutations, respectively." (PMID 29058119, 2018). "The association between circRNA expression and prognosis factors of PTC, such as tumor size, tumor stage, LNM, and BRAF mutation, remains unclear." (PMID 30123704, 2018). "Our data suggests that tumor progression is independent of the presence of BRAF V600E mutation since progression free survival rates were very similar between the two groups: BRAFwt and BRAFmut." (PMID 30558563, 2018). "Therefore, the discovery of selective BRAF inhibitors represented a turning point in the management of this aggressive form of tumor." (PMID 30483135, 2018). "The present study demonstrated that EPDR1 hypermethylation is significantly correlated with a negative node status, a lower tumor stage, BRAF and TGFβR2 mutations and better prognosis in CRC patients." (PMID 30360391, 2018). "Interestingly, we found that Cetuximab exerted stronger tumour growth inhibitory effects on mutant BRAF (RKO) cell lines in vivo than in vitro." (PMID 29755114, 2018). "One particular focus of the present study is the group of patients with BRAF-mutant tumours." (PMID 29872151, 2018). "Moreover, BPTES enhances the anti-tumor activity of BRAF inhibitors, underscoring the importance of glutamine in mediating BRAF inhibitor resistance." (PMID 30456204, 2018). "Moreover, primary corticotroph tumor cells harboring BRAF V600E are sensitive to the BRAF inhibitor vemurafenib." (PMID 30093687, 2018). "We identified genes that exhibited average gene expression level differences between BRAF V600E+ and BRAF− tumor samples in the entire TCGA data using DESeq (FDR adjusted p < 0.05) and edgeR (FDR < 0.01) between and identified 26 differentially expressed genes (DEGs)." (PMID 30042785, 2018). "However a short interval scan done at four weeks demonstrated rapid tumor progression on vemurafenib alone indicating that her tumor retained its previously acquired resistance to the BRAF inhibitor." (PMID 28094001, 2017). "Based on the BRAF mutation it was concluded that the subpleural tumour was an intrapulmonary metastasis rather than a separate synchronous tumour." (PMID 28347348, 2017). "Mutations in BRAF were identified in 8.4% and KIT in 7.0% of tumor samples." (PMID 28380455, 2017). "We observed a perfect match (100% specificity and sensitivity of the BEAMing technique compared to Ion Torrent and Cobas FDA-approved tumor mutation assessment kits) in the results of our analysis of KRAS, NRAS, PIK3CA and BRAF mutations in tumor and prior treatment plasma samples." (PMID 27852040, 2017). "Furthermore, increased CD8+ T cell tumor infiltration was observed in early tumor samples in patients treated with BRAF inhibition." (PMID 28239469, 2017).
tumor (continued). "There was no apparent association between BRAF mutation status and clinical outcome, and tumour reduction was observed in patients both with and without detectable BRAF mutations in their tumours." (PMID 28103611, 2017). "In support of the hypothesis that LCH is a clonal neoplastic disorder, recent discoveries have shown the V600E mutation in the BRAF oncogene in LCH cells, the same mutation found in other tumor types." (PMID 28482919, 2017). "In summary, BRAF V600E-activated MAP kinase pathway causes hypomethylation and overexpression of WIPF1; WIPF1 then functions like an oncoprotein to robustly promote aggressive cellular and tumor behaviors of PTC." (PMID 27863429, 2017). "Celecoxib significantly delayed tumor acceleration by the BRAF inhibitor PLX7420 or vemurafenib." (PMID 28865485, 2017). "Melanocytes displayed normal skin localization and neither nevi, nor tumours developed from BRAF-deficient animals." (PMID 28497782, 2017). "In our study, we observed that none of the two POLE‐positive tumors presented NRAS or BRAF mutations, but tumor T286 exhibited the p.Glu542Lys PIK3CA mutation and tumor T368 displayed the p.Lys117Asn KRAS mutation." (PMID 29072370, 2017). "The mutational status of BRAF and NRAS in the four PTC variants (cPTC, PTMC, PTMC-FV and PTC/FV) was compared to the clinicopathological parameters, including age, gender, tumor size, extracapsular extension, lymphovascular involvement, lymph node metastasis, and multifocality." (PMID 28680105, 2017). "Another BRAF inhibitor resistance mechanism is based on the tumour microenvironment." (PMID 28708099, 2017). "In our opinion, the individually tailored treatment decision and the consideration of more aggressive approach may be needed in the BRAF mutated tumours and alternative chemotherapy in the MSI tumours." (PMID 28067827, 2017). "Fusion-positive nuclei in tumor sections display the BRAF break apart pattern; two pairs of merged (yellow) or adjacent signals green/red (representing 5’/3’wt BRAF alleles), and one additional split red (3’) signal indicating a duplicated copy of the 3’ BRAF region." (PMID 28448514, 2017). "In agreement with the theory that MMR status links prognosis with BRAF mutational status, we found a statistically significant negative prognostic value of BRAF mutation in the serum from patients with pMMR in tumor." (PMID 28378527, 2017). "In a direct comparison of the single-cell data and an immunofluorescence analysis of the original tumor of the BRAF/NRAS wild type tumor sample, we provided strong evidence that the cell composition revealed by single-cell RNA-seq reflects the actual situation in the original primary tissue." (PMID 27903987, 2017). "Besides, it has also been reported that BRAF inhibition induced upregulation of MHC class I expression in tumor cells and facilitated antigen presentation and recognition." (PMID 29156850, 2017). "Although further quantitative analysis is needed, it seems that when high levels of MerTK are present before treatment starts, the tumor cells may take advantage of other mechanisms to survive BRAF or combined BRAF/MEK blockade." (PMID 29050198, 2017). "This EMT-related phenotypic change and tumor cell plasticity shown in the present study therefore, can be suggested furthermore as another acquired resistance mechanism to BRAF inhibitor, so further in-depth studies are warranted to elucidate the precise underlying mechanism." (PMID 27880942, 2017). "Concomitant loss of BRAF and CRAF in melanocytic lineage completely reversed the hyperpigmented phenotype without affecting the normal development of melanocytes and prevented tumour onset." (PMID 28497782, 2017). "When BRAF is blocked, tumor cells may increase PDGFR-β and IGF-1R expression, leading to persistent PI3K/AKT-signaling that prevents apoptosis and promotes survival." (PMID 29100459, 2017).
tumor (continued). "In this manuscript we describe a tumor with a novel fusion of BRAF with GIT2, hypothesized to result in activation of MAPK in a similar fashion as in PAs with the canonical KIAA1459-BRAF fusion." (PMID 29141672, 2017). "Taken together with other studies, these results suggest that combining ERK1/2 pathway inhibitors with ER stressors, or ER stress mimetics that influence specific arms of the UPR, may have therapeutic potential in tumours with RAS, BRAF or MEK mutations." (PMID 28931068, 2017). "None of the long survivors had a tumor exhibiting both a BRAF mutation and high Ki67 positivity, compared to 30% (7/23) of the short survivors (p = 0.011)." (PMID 28851300, 2017). "On contrary, the levels of cfDNA mutations in patients without a prior KRAS/NRAS/BRAF/PIK3CA tumor mutation were 10-fold lower than the mutation cutoff (p = 0.002)." (PMID 27852040, 2017). "All BRAF and KRAS mutations identified in the exome sequencing data of the polyps were confirmed by targeted molecular analysis which demonstrates the ability of our approach to identify relevant variants with a fraction of variant reads 3 5% in tumour DNA." (PMID 29213343, 2017). "Factors that were associated with statistically significantly worse OS in this analysis included an age of <50 years (p=0.016), right-sided tumor origin (p<0.001), poor differentiation (p<0.001), KRAS mutations (p<0.001), BRAF mutations (p=0.004), and PIK3CA mutations (p=0.007)." (PMID 28424412, 2017). "Based on these results, it could be inferred that targeting glucose metabolism in CRC patients bearing KRAS- or BRAF-mutant tumors may be a safer and more effective strategy compared to utterly impairing tumor angiogenesis." (PMID 28445144, 2017). "To further investigate whether circulating HGF versus HGF present in the tumor microenvironment could mediate resistance to BRAF inhibition, we modeled systemic and local/tumor HGF expression systems in mice." (PMID 28147313, 2017). "Multiple resistant mechanisms to BRAF inhibitors have been discovered which include epigenetic (hypermethylation of CpG islands), genomic (Hippo effector YAP, BRAF splice variants, BRAF gene amplification, mutations in RAS-RAF-MEK-ERK pathway) and phenotypic (tumor heterogeneity and plasticity)." (PMID 29179510, 2017). "A proportion of cells expressing mutant or amplified BRAF become dependent on BRAF inhibition for a selective advantage, and cessation of drug administration leads to tumor regression; a staggered regimen has been shown to delay onset of resistance in both mice and human xenograft cell lines." (PMID 29179523, 2017). "In this study, we report that BRAF-activated BANCR may function as a tumor suppressor via the ERK/MAPK signaling pathway in PTC." (PMID 27462868, 2017). "Therefore dual inhibition of BRAF and c-Met led to sustained treatment response, thereby maximizing the specific anti-tumor effect of targeted therapy." (PMID 27880942, 2017). "Overall our data lead to a model, whereby in tumours on treatment with BRAF inhibitor‐induced MITF up‐expression in MITF‐high cells increases intra‐tumour EDN1 levels, which can act on MITF‐high (paracrine or autocrine) as well as AXL‐high cells to re‐activate ERK." (PMID 28606996, 2017). "This has been well studied and documented in various BRAF-driven neoplasms." (PMID 28903326, 2017). "Since BRAF and NRAS hotspot mutations are almost mutually exclusive there is close to a 97.6% probability that we would have found either a BRAF or an NRAS hotspot mutation in at least one of the tumours." (PMID 28806732, 2017). "If BRAF V600E mutation is found, no further testing is required, as the tumor is presumed to be sporadic CRC." (PMID 28259170, 2017).
tumor (continued). "Additionally, tumours and cell lines with NF1 lesions were found to lack KRAS and BRAF mutations, whilst exhibiting Ras pathway activation." (PMID 28637487, 2017). "Multivariate analysis revealed a negative predictive value of RAS and BRAF tumor mutations with respect to first-line Bmab treatment." (PMID 28068936, 2017). "The NCCN guidelines state that all patients with metastatic CRC should have tumor tissue genotyped for KRAS, NRAS, and BRAF mutations, and patients with any known KRAS or NRAS mutation should not be treated with anti-EGFR therapy such as cetuximab and panitumumab." (PMID 29212173, 2017). "Dual EGFR and MEK and/or mTOR inhibitors showed improved response in tumor models harboring aberrant biomarkers, such as RAS, BRAF and PIK3CA mutations, suggesting that they might prevent the activation of resistance pathways." (PMID 28002810, 2017). "However, the effects of single CRAF deletion were very weak compared to that of the double BRAF/CRAF KO, and far from sufficient to block tumour growth, clearly indicating a compensatory effect implicating BRAF." (PMID 28497782, 2017). "CRIS-A is highly enriched for BRAF-mutated MSI tumours and KRAS-mutated MSS tumours, for which no targeted treatment options are currently available." (PMID 28561063, 2017). "The tumor was also tested for mutations in exons 2, 3, and 4 of the KRAS and NRAS genes, codon 600 of the BRAF gene, and exons 10 and 21 of the PIK3CA gene, and showed a mutation in PIK3CA exon 10, namely the c.1624G>A, p.Glu542Lys (previously reported by our group 15)." (PMID 29072370, 2017). "For patients with a BRAF wild-type tumor, aspirin use after diagnosis showed a RR for overall survival of 0.74 (95% CI 0.54–1.00), and when adjusted for potential confounders this effect was more pronounced with an adjusted RR of 0.60 (95% CI 0.44–0.83, p = 0.002)." (PMID 28125730, 2017). "Of these 45 BRAF-grouped tumours (B or BP), only 9 (20%) were metastatic." (PMID 27302369, 2016). "One possible mechanism of two identical somatic mutations arising in two different tumors is that BRAF mutations can be found in tumor-surrounding nontumoral tissues." (PMID 27656301, 2016). "Even though the tumor biology and prognosis of patients with concomitant KRAS and BRAF mutations have been still uncertain, previous research suggests that these concomitant mutations are associated with tumor progression such as lymph node metastasis and higher T stage." (PMID 26991109, 2016). "Moreover, we propose to explore the biological meaning of BRAF immunohistochemical labeling both as a marker predictive of response to target therapy and as a player of acquired tumor drug resistance." (PMID 27863476, 2016). "Earlier, we assessed whether BRAF activation alone would be sufficient for tumor formation, by inducing expression of BrafV600E under control of its endogenous promoter in Gfap+ cells, by breeding BrafCA/+ hemizygous and hGFAP-cre transgenic mice." (PMID 27713119, 2016). "EGFR expression was analysed in tumours from three independent patient cohorts; cohort 1 (n = 533), cohort 2 (n = 259) and cohort 3 (n = 310), previously analysed for immunohistochemical PODXL expression and KRAS and BRAF mutations (cohort 1 and 3)." (PMID 27160084, 2016). "The BRAF V600E mutation was associated with older age and conventional subtype but not with more well-established prognosticators such as tumor size, multifocality, or TNM stage." (PMID 27064992, 2016). "If only the minimally invasive adenocarcinoma had been tested, we would have mistakenly assumed that the patient's tumor had no BRAF mutation." (PMID 27597976, 2016).